KNG1 (kininogen 1)
Description:
Kininogens are inhibitors of thiol proteases. HMW-kininogen plays an important role in blood coagulation by helping to position optimally prekallikrein and factor XI next to factor XII; HMW-kininogen inhibits the thrombin- and plasmin-induced aggregation of thrombocytes. LMW-kininogen inhibits the aggregation of thrombocytes. LMW-kininogen is in contrast to HMW-kininogen not involved in blood clotting. [Bradykinin]: The active peptide bradykinin is a potent vasodilatator that is released from HMW-kininogen shows a variety of physiological effects: (A) influence in smooth muscle contraction, (B) induction of hypotension, (C) natriuresis and diuresis, (D) decrease in blood glucose level, (E) it is a mediator of inflammation and causes (E1) increase in vascular permeability, (E2) stimulation of nociceptors (4E3) release of other mediators of inflammation (e.g. prostaglandins), (F) it has a cardioprotective effect (directly via bradykinin action, indirectly via endothelium-derived relaxing factor action).
Synonyms: HMWK; BDK; KNG; BK; HAE6; HK
Tractability: Small molecule: a structure with a bound ligand is known. Antibody: its Gene Ontology location is reachable by antibodies, with high confidence; UniProt places it where antibodies can reach, with medium confidence; UniProt predicts a signal peptide or a membrane-spanning region. PROTAC: its protein half-life has been measured.
Safety:
Unwanted effects reported when the protein is acted on. In parentheses: how it was acted on, where the effect was seen, and who reports it.
venous thrombosis (source: ClinPGx)
Gene: Protein-coding gene on chromosome 3 (186,717,329 to 186,744,410, forward strand). Ensembl gene ENSG00000113889.
Subcellular location: Secreted, extracellular space
Pathways (Reactome):
Signal Transduction: G alpha (i) signalling events; G alpha (q) signalling events; Peptide ligand-binding receptors
Hemostasis: FXIIa, PKa-dependent activation of coagulation pathway; Platelet degranulation
Immune System: FXIIa activates plasma kallikrein-kinin system; Regulation of FXIIa and plasma kallikrein activity
Metabolism of proteins: Post-translational protein phosphorylation; Regulation of Insulin-like Growth Factor (IGF) transport and uptake by Insulin-like Growth Factor Binding Proteins (IGFBPs)
Gene Ontology:
Molecular function: cysteine-type endopeptidase inhibitor activity; hormone activity; protein binding; signaling receptor binding; heparin binding; zinc ion binding
Biological process: negative regulation of blood coagulation; negative regulation of cell adhesion; negative regulation of proteolysis; positive regulation of cytosolic calcium ion concentration; vasodilation; positive regulation of apoptotic process; negative regulation of multicellular organismal process; signal transduction
Cellular component: blood microparticle; extracellular exosome; extracellular matrix; extracellular region; endoplasmic reticulum lumen; plasma membrane; platelet alpha granule lumen
Genetic constraint (gnomAD): Loss-of-function variants: 12 observed, 33.81 expected, observed/expected ratio (o/e) 0.35, 90% interval 0.23 to 0.57. The upper end of that interval is the gene's LOEUF score, 0.57, which puts it in group 2 of 6, group 1 being the genes least tolerant of losing a copy. Missense variants: 660 observed, 728.44 expected, observed/expected ratio (o/e) 0.91, 90% interval 0.85 to 0.97. Synonymous variants: 243 observed, 257.6 expected, observed/expected ratio (o/e) 0.94, 90% interval 0.85 to 1.05.
Gene-disease validity (ClinGen):
ClinGen rates the evidence that KNG1 causes each of these diseases.
congenital high-molecular-weight kininogen deficiency (autosomal recessive): Definitive. A rare autosomal recessive inherited disorder characterized by prolonged partial thromboplastin time and absence of bleeding diathesis.
Homologues: Orthologues: chimpanzee KNG1 (98% identical), macaque KNG1 (93% identical), pig KNG1 (72% identical), dog KNG1 (72% identical), rabbit KNG1 (70% identical), guinea pig KNG1 (60% identical), mouse Kng1 (59% identical), rat Kng2l1 (59% identical), mouse Kng2 (57% identical), rat Kng1 (57% identical), rat Kng2 (56% identical), tropical clawed frog kng1 (26% identical). Paralogues in human: HRG (14% identical), FETUB (11% identical), AHSG (9% identical).
Diseases named in the same sentence as KNG1 in open-access papers:
KNG1 is named in the same sentence as 191 diseases in open-access papers, as found by Europe PMC text mining. Sharing a sentence is not in itself a finding about the gene and the disease. The quoted sentences say what the papers report.
COVID-19 (32 papers, 2020 to 2025). A disease caused by infection with severe acute respiratory syndrome coronavirus 2. "Since the kinin-kallikrein system plays a role in the pathophysiology of ALI, we hypothesize that EVs carrying kininogen-1 may enter the bloodstream, contribute to systemic inflammation, and consequently increase the risk for thrombosis in COVID-19." (PMID 35929616, 2022). "Moreover, exosomal kininogen-1 may be yet another biomarker of thrombosis risk in COVID-19 patients, because the kinin-kallikrein system is activated by Factor XII of the coagulation cascade." (PMID 35929616, 2022). "KNG1, a precursor to bradykinin and a component of the intrinsic coagulation cascade, is elevated in COVID-19 and contributes to both inflammation and thrombosis." (PMID 40821834, 2025). "PON1 and KNG1 levels significantly decreased in moderate patients compared to controls and showed a tendency towards a significant decrease in our severe COVID-19 patients compared to healthy controls." (PMID 38791465, 2024). "A recent study has also revealed a similar phenomenon, in which the increase of KNG1 protein in patients infected with COVID-19 was accompanied by a decrease in immune system proteins." (PMID 37442062, 2023). "KNG1, with the highest degree centrality, is the precursor for bradykin synthesis, and is involved in the coagulation system dysfunction of severe COVID-19." (PMID 33716737, 2021). "In our serum proteomics data, the abundances of AHSG, FETUB, HRG, and KNG1 are found to be highly correlated in each of the sampled COVID-19 patients and are consistently higher in the survivors." (PMID 34226277, 2021). "On the other hand, the proteins shown in blue were increased in the recovered group, for instance, THBS1, an antiangiogenic protein, which is increased in the serum of asymptomatic COVID-19 patients, as well as other proteins related to endothelial dysfunction or KNG1, a proinflammatory protein." (PMID 37628421, 2023). "Our data showed a two-fold up-regulation of Kininogen-1 in the exosomes of COVID-19 patients." (PMID 33693030, 2021). "A recent study has reported the presence of an abundant amount of coagulation-related protein Kininogen-1 in EVs, such as exosomes isolated from COVID-19 patients, and suggested that exosomes may act as a reserve of Kininogen-1." (PMID 34638812, 2021). "In our study ACE, REN, INS, KNG1, and AGT showed the highest connectivity within the complete ACE2 network and association with enriched diseases that are known to be a risk factor for a severe course of COVID-19." (PMID 33233425, 2020). "In the coagulation pathway, we found that IVIG treatment decreases KNG1 and ACTB and increased FGA relative to COVID-19 controls, although the variance in FGA levels was similar between groups." (PMID 40821834, 2025). "The induction of KNG1, KLK1, and BDKRB2 in primary nasal samples of SARS-CoV-2-positive study participants is evidence for an autocrine bradykinin effect via B2R that is triggered locally during COVID-19 disease." (PMID 35247068, 2022). "Moreover, the plasma proteins HRG, FETUB, KNG1, LCAT, AHSG, and FN1 increase over time in abundance in the Munich cohort, thus suggesting their regulation during COVID-19 disease development." (PMID 34226277, 2021). "A recent study on a cohort of 66 COVID-19 patients admitted to the intensive care unit showed that the KKS was strongly activated, which was reflected in the consumption of factor XII (F12), pre-kallikrein (KLKB1), and high-molecular-weight-kininogen (HMWK; KNG1)." (PMID 35247068, 2022). "Consistently, proteomic and metabolomics data from CMs revealed several genes (KNG1, TXNIP, ITIH4, TIMP1, SERPING1/2/3, ITGA1, ADAR, and CLIC5 etc.)and molecules (adenosine and inosine) were related with platelet activation, thus, adding antiplatelet might be a possible therapeutic for COVID-19." (PMID 35903092, 2022).
angioedema (27 papers, 2010 to 2026). Swelling involving the deep dermis, subcutaneous, or submucosal tissues, representing localized edema. "ReferenceBork K, Wulff K, Rossmann H, Steinmüller‐Magin L, Brænne I, Witzke G, Hardt J. Hereditary Angioedema cosegregating with a novel kininogen 1 gene mutation changing the N‐terminal cleavage site of bradykinin." (PMID 38124188, 2023). "KNG1 is a protein coding gene, and has association with some diseases including angioedema and high molecular weight kininogen deficiency." (PMID 35675043, 2022). "Targeted re-sequencing of five HAE-associated genes (SERPING1, F12, PLG, ANGPT1, and KNG1) was performed in 212 ACEi/ARB-induced angioedema patients recruited in Germany/Austria, Sweden, and Denmark, and in 352 controls from a German cohort." (PMID 35923707, 2022). "In conclusion, the present analyses identified no known disease-causing HAE variant in SERPING1, F12, PLG, ANGPT1, or KNG1 in a cohort of around 200 patients with ACEi/ARB-induced angioedema." (PMID 35923707, 2022). "Whereas, deleterious variations in F12, KLKB1, and KNG1 could impair BK formation, working as a protective factor in BK-mediated angioedema." (PMID 30847342, 2019). "Apart from these cases, hereditary angioedema is explained by other genetical defects affecting factor XII, angiopoietin-1, plasminogen, and kininogen 1 genes." (PMID 40599632, 2025).
hereditary angioedema (24 papers, 2011 to 2026). Hereditary angioedema (HAE) is a genetic disease characterized by the occurrence of transitory and recurrent subcutaneous and/or submucosal edemas resulting in swelling and/or abdominal pain. "The group will then develop pathogenicity classification rules to curate variants in genes responsible for Hereditary Angioedema with normal C1-INH (nl-C1-INH-HAE), such as F12, PLG, ANGPT1, KNG1, MYOF, and HS3ST6 (OMIM: 610618, 619360, 619361, 619363, 619366, 619367)." (PMID 38124188, 2023). "Hereditary angioedema can occur with normal C1-INH, due to mutations in other genes involved in bradykinin overproduction, e.g. factor XII (Hageman Factor), plasminogen gene, angiopoeitin-1 gene and kininogen-1 gene, but there are still many unclassified cases of hereditary angioedema." (PMID 36238930, 2022). "Hereditary angioedema due to C1 Inhibitor deficiency shares a common kinin dependency with other HAE situations: F12-HAE, PLG-HAE, KNG1-HAE, ANGPT1-HAE, and HS3ST6-HAE, but not with MYOF-HAE, U-HAE." (PMID 35958943, 2022).
colorectal cancer (17 papers, 2013 to 2024). A primary or metastatic malignant neoplasm that affects the colon or rectum. "KNG1 has recently been identified as a biomarker for diseases, such as colorectal cancer, oral cancer, gliomas, and many others." (PMID 38340139, 2024). "KNG1 has been identified as a biomarker for colorectal cancer, ovarian carcinoma, and many other cancers, owing to its ability in modulating the progression of a wide range of diseases and cancers." (PMID 36550594, 2023). "On the contrary, other researchers have found that KNG1 expression was significantly increased in colorectal cancer lesions." (PMID 36419007, 2022). "Recently, KNG1 was also considered a serum biomarker for the early detection of colorectal cancer and advanced colorectal adenoma." (PMID 35401213, 2022). "KNG1, a cysteine proteinase, has identified as a serum biomarker for the early detection of advanced colorectal adenoma and colorectal cancer, as well as a potential prognostizc biomarker for oral cancer." (PMID 35113866, 2022). "Several studies showed that KNG1 had higher content in urine and serum from different cancers, and the content of KNG1 in serum was lower before operation than after operation in colorectal cancer patients." (PMID 35401213, 2022). "KNG1 was significantly overexpressed in colorectal cancer cells compared to normal and dysplastic tissues." (PMID 34067437, 2021). "KNG1 was studied as the core gene and downregulated in the glioma cells, which was also identified as a serum biomarker for colorectal cancer." (PMID 32090070, 2020). "Previous work showed that KNG1 can be used as a serum biomarker for colorectal cancer." (PMID 36785669, 2023). "Besides, KNG1 has been identified as a biomarker for colorectal cancer, ovarian carcinoma, etc., with the ability to modulate the progression of different diseases." (PMID 36550594, 2023). "Furthermore, KNG1 has been suggested as a potential biomarker for early colorectal cancer diagnosis." (PMID 34688260, 2021). "Furthermore, higher expression of kininogen 1 is recently reported as a serum biomarker of advanced colorectal adenoma, colorectal cancer and prognostic marker of oral cancer." (PMID 33585190, 2020). "KNG1 was identified as a potential marker of early colorectal cancer stages." (PMID 29740512, 2018). "Post-translational modification in KNG1, AHSG and downregulation of ITIH2 has been reported in colorectal cancer." (PMID 35109816, 2022).
glioma (15 papers, 2009 to 2025). A benign or malignant brain and spinal cord tumor that arises from glial cells (astrocytes, oligodendrocytes, ependymal cells). "During this search, we identified KNG1, a molecule that has been linked to the progression of glioma, as a putative candidate." (PMID 40376586, 2025). "In this study, we obtained 2930 DEGs based on TCGA and finally identified KNG1 as the core gene associated with survival of glioma patients." (PMID 30068373, 2018). "To investigate the impact of ADORA1 and KNG1 on glioma proliferation, we developed an in-situ glioma model using GL261 cells implanted in C57 mice." (PMID 40376586, 2025). "ADORA1 suppresses the expression of KNG1 in glioma, consequently impeding the anti-tumor immune response within the tumor microenvironment." (PMID 40376586, 2025). "Our results indicated that ADORA1 was highly expressed in gliomas and that ADORA1 overexpression promoted glioma progression by inhibiting KNG1." (PMID 40376586, 2025). "KNG1, a precursor of kinins in the kallikrein-kinin system, induces apoptosis and exerts anti-cancer effects on glioma." (PMID 40376586, 2025). "Inhibiting ADORA1 promoted glioma cell death via KNG1, increased T-cell recruitment, and improved glioma responsiveness to anti-PD1 therapy." (PMID 40376586, 2025). "Our findings indicate that ADORA1 overexpression facilitated glioma growth and decreased survival time in the mice, whereas KNG1 overexpression mitigated these effects." (PMID 40376586, 2025). "The findings indicate that ADORA1 suppresses the expression of KNG1 in glioma, consequently impeding the anti-tumor immune response within the tumor microenvironment." (PMID 40376586, 2025). "In vitro and in vivo experiments revealed that ncRNA linc01018 regulates the malignant progression of gliomas through the miR-942-5p/KNG1 axis, enhancing glioma cell migration and invasion while modulating the expression of metastasis-related genes." (PMID 38967893, 2024). "After performing a series of in vitro and in vivo experiments, we unraveled that LINC01018/miR‐942‐5p/KNG1 axis regulated the malignant development of glioma cells, revealing a new regulatory pathway for glioma." (PMID 36550594, 2023). "Silent LINC01018 or KNG1 and miR‐942‐5p mimic enhanced the migration, invasion, and proliferation of glioma cells, and regulated the expressions of metastasis‐related and proliferation‐related genes." (PMID 36550594, 2023). "The impacts of KNG1 combined with miR‐942‐5p on glioma cells were gauged by detecting changes in migration, invasion, and proliferation rates." (PMID 36550594, 2023). "Since the inhibitory effect of KNG1 on glioma has been proved, this study further explores the regulation of the lncRNA/miRNA axis on KNG1 in glioma." (PMID 36550594, 2023). "In this study, the effects of KNG1 on the biological functions of glioma cells were enriched, further suggesting the inhibitory effect of KNG1 on the development of glioma." (PMID 36550594, 2023). "Correspondingly, the transcription and translation levels of KNG1 in glioma cells were remarkably decreased compared with those in NHA cells (p < 0.001), while the level of miR‐942‐5p in glioma cells was signally enhanced (p < 0.05)." (PMID 36550594, 2023). "All these discoveries implied that miR‐942‐5p regulated the malignant biological activities of glioma cells by targeting KNG1." (PMID 36550594, 2023). "After verification of the inhibitory effects of KNG1 on proliferation, migration, and invasion of T98G and LN‐229 glioma cells, the miRNA‐targeting KNG1 was detected." (PMID 36550594, 2023). "Since the inhibitory effect of KNG1 on glioma had previously been proved, this study further explored the regulation of lncRNA/miRNA axis on KNG1 in glioma." (PMID 36550594, 2023). "Silenced LINC01018 or KNG1 and miR‐942‐5p mimic enhanced the migration, invasion, and proliferation of glioma cells and regulated the expressions of metastasis‐related and proliferation‐related genes." (PMID 36550594, 2023).